NECAP2 (NECAP endocytosis associated 2)
Description:
Involved in endocytosis.
Synonyms: FLJ10420
Tractability: Antibody: UniProt places it where antibodies can reach, with medium confidence; its Gene Ontology location is reachable by antibodies, with medium confidence. PROTAC: ubiquitination databases record sites on it; its protein half-life has been measured.
Gene: Protein-coding gene on chromosome 1 (16,440,707 to 16,460,081, forward strand). Ensembl gene ENSG00000157191.
Subcellular location: Cytoplasmic vesicle, clathrin-coated vesicle membrane; Cell membrane
Subcellular location (Human Protein Atlas): Endoplasmic reticulum
Pathways (Reactome):
Vesicle-mediated transport: Cargo recognition for clathrin-mediated endocytosis; Clathrin-mediated endocytosis
Gene Ontology:
Molecular function: protein binding
Biological process: endocytosis; vesicle-mediated transport
Cellular component: clathrin vesicle coat; clathrin-coated pit; clathrin-coated vesicle membrane; membrane; plasma membrane
Genetic constraint (gnomAD): Loss-of-function variants: 35 observed, 35.2 expected, observed/expected ratio (o/e) 0.99, 90% interval 0.76 to 1.32. The upper end of that interval is the gene's LOEUF score, 1.32, which puts it in group 5 of 6, group 1 being the genes least tolerant of losing a copy. Missense variants: 300 observed, 344.93 expected, observed/expected ratio (o/e) 0.87, 90% interval 0.79 to 0.96. Synonymous variants: 117 observed, 131.38 expected, observed/expected ratio (o/e) 0.89, 90% interval 0.77 to 1.04.
Homologues: Orthologues: pig NECAP2 (92% identical), guinea pig NECAP2 (90% identical), mouse Necap2 (89% identical), chimpanzee NECAP2 (86% identical), macaque NECAP2 (86% identical), dog SZRD1 (83% identical), rat Necap2 (80% identical), rabbit NECAP2 (73% identical), zebrafish necap2 (60% identical), Drosophila melanogaster CG9132 (50% identical), Caenorhabditis elegans ncap-1 (43% identical). Paralogues in human: NECAP1 (64% identical).
Diseases named in the same sentence as NECAP2 in open-access papers:
NECAP2 is named in the same sentence as 6 diseases in open-access papers, as found by Europe PMC text mining. Sharing a sentence is not in itself a finding about the gene and the disease. The quoted sentences say what the papers report.
glioma (2 papers, 2022 to 2023). A benign or malignant brain and spinal cord tumor that arises from glial cells (astrocytes, oligodendrocytes, ependymal cells). "In glioma, the overexpression of NECAP2 has a remarkably higher risk of developing malignant behavior and a worse prognosis." (PMID 37239411, 2023). "NECAP2 overexpression was linked to malignant characteristics and unfavorable prognosis in glioma patients." (PMID 36531205, 2022). "Glioma patients with NECAP2 overexpression have a remarkably higher risk of developing malignant behavior and a worse prognosis." (PMID 36531205, 2022). "Therefore, we sought an in-depth comprehension of NECAP2 level in gliomas and its association with malignant characteristics and glioma patients' prognoses." (PMID 36531205, 2022). "We then evaluated the link between NECAP2 expression levels and the level of TIICs in glioma tissues." (PMID 36531205, 2022). "Based on these findings, NECAP2 seems to be a promising candidate biomarker for assessing the prognosis of glioma and immune infiltration." (PMID 36531205, 2022). "The correlation between the expression levels of NECAP2 and the prognosis of glioma patients was identified." (PMID 36531205, 2022). "Importantly, NECAP2 overexpression is linked to the immune infiltration level of T cells, mast cells, neutrophils, NK cells, DCs, cytotoxic cells, DC, eosinophils, macrophages, Treg, and other immune cells and is intimately linked to the overall immune infiltration level of glioma." (PMID 36531205, 2022). "We found for the first time that NECAP2 level was elevated in gliomas and that this upregulation increased as the tumor grade increased." (PMID 36531205, 2022). "Univariate and multivariate Cox regression analyses showed that NECAP2 independently served as a predictive biological marker for glioma." (PMID 36531205, 2022). "In vitro wound-healing and Transwell assay confirmed that NECAP2 promotes glioma cell migration and invasion." (PMID 36531205, 2022). "In the present study, the expression level of NECAP2 was shown for the first time to be highly elevated in gliomas and increased with tumor grade." (PMID 36531205, 2022). "We used Biodatabase to determine that glioma tissues express NECAP2 and screened the NECAP2 coexpressed genes related to oxidative stress." (PMID 36531205, 2022). "In vitro wound healing and transwell assays confirmed that NECAP2 promotes glioma cell migration and invasion." (PMID 36531205, 2022). "Therefore, NECAP2 strongly correlates with the overall immune infiltration level of glioma and can independently serve as a prognostic biological marker for glioma patients." (PMID 36531205, 2022). "Furthermore, to examine the predictive effectiveness of NECAP2 for high infiltration levels in gliomas, we examined the correlation between NECAP2 and infiltration degrees of various immune cells." (PMID 36531205, 2022). "We further investigated the link between NECAP2 expression and prognosis in glioma patients." (PMID 36531205, 2022). "Western blotting showed that NECAP2 was overexpressed in glioma patients." (PMID 36531205, 2022). "Consequently, we examined the link between NECAP2 expression in glioma, tumor-infiltrating immune cells (TIICs), and prognosis." (PMID 36531205, 2022). "Therefore, our results indicate that NECAP2 strongly correlates with the overall immune infiltration level of glioma and could independently serve as a prognostic biological marker for glioma patients." (PMID 36531205, 2022). "It should also be noted that the function of KCNC1, KCNT1, RIMS2, NECAP2, GNG5, SCAMP2, GNAI3 genes is also correlated with membrane function in low-grade gliomas." (PMID 37239411, 2023).
liver cancer (1 paper, 2021). An epithelial or non-epithelial malignant neoplasm that arises from the liver. "According to Human Protein Atlas, high expression of NECAP2 is a favorable and unfavorable prognostic factor in colorectal and liver cancer, respectively." (PMID 33504899, 2021).
low grade glioma (1 paper, 2022). A grade I or grade II glioma arising from the central nervous system. "Here, we systematically evaluated the differences (variations) in NECAP2 expression for low-grade glioma (LGG) and pan-cancer in the LGG dataset of The Cancer Genome Atlas (TCGA) utilizing bioinformatics methods." (PMID 36531205, 2022).
cancer (2 papers, 2021 to 2022). A tumor composed of atypical neoplastic, often pleomorphic cells that invade other tissues. "Combined with marker genes in The Immune Landscape of Cancer, we analyzed the Pearson correlations between NECAP2 and five immune pathways, and the correlation heat map suggested significant correlations." (PMID 36531205, 2022). "We evaluated NECAP2 mRNA levels in pan-cancer tissues using the clinical data of 528 LGG patients acquired from the TCGA-LGG database." (PMID 36531205, 2022). "We integrated pan-cancer multidimensional data to analyze the correlation of NECAP2 with DNAs tumor stemness score and MSI score calculated from methylation signatures and significant gene mutations associated with NECAP2." (PMID 36531205, 2022). "We employed CIBERSORT and ESTIMATE techniques to examine the link between NECAP2 and cancer immune infiltration." (PMID 36531205, 2022). "NECAP2 function is also essential for the fast recycling of integrin αvβ3 and integrin αvβ3-dependent migration and cancer cell invasion." (PMID 33504899, 2021). "Pearson correlation of NECAP2 in pan-cancer was calculated from gene expression data." (PMID 36531205, 2022). "The significant differences in NECAP2 in pan-cancer are shown in a lollipop plot." (PMID 36531205, 2022). "We integrated multidimensional data to analyze the pan-cancer function and significance of NECAP2." (PMID 36531205, 2022). "Our study also thoroughly examined the immune significance of NECAP2 in the TCGA-LGG samples, using CIBERSORT and ESTIMATE to explore the correlation between NECAP2 and cancer immune infiltration." (PMID 36531205, 2022). "Taken together, our results indicate that NECAP2 might interface with components of the TME, take part in various cancer-related, oxidative stress-related, and immune-related pathways, and contribute to the advancement of LGG." (PMID 36531205, 2022).
tumor (2 papers, 2021 to 2022). "Conversely, we identified NECAP2 (NECAP endocytosis associated 2) as up-regulated in tumor stroma and correlated with higher tumor grade when measured directly in the stroma (p-value = 0.01, average ρ = 0.30) but only slightly when measured in bulk (p-value = 0.03, ρ = 0.05)." (PMID 34282769, 2021). "IHC staining illustrated that the NECAP2 protein expression enhanced with the development of tumor malignancy (marked by changes in histological grade)." (PMID 36531205, 2022). "IHC staining results illustrated an elevation in the NECAP2 protein expression level with the development of tumor malignancy." (PMID 36531205, 2022). "The findings of the IHC staining confirmed that the expression of the NECAP2 protein was enhanced as the malignancy of the tumor increased." (PMID 36531205, 2022). "Similarly, NECAP2 is among the top up-regulated genes in tumor stroma only, correlating with a higher grade." (PMID 34282769, 2021).
NECAP2 also shares sentences with these, for which no sentence is quoted: Pan (1 paper).